TMTC2 (transmembrane O-mannosyltransferase targeting cadherins 2)
Description:
Transfers mannosyl residues to the hydroxyl group of serine or threonine residues. The 4 members of the TMTC family are O-mannosyl-transferases dedicated primarily to the cadherin superfamily, each member seems to have a distinct role in decorating the cadherin domains with O-linked mannose glycans at specific regions. Also acts as O-mannosyl-transferase on other proteins such as PDIA3.
Synonyms: DKFZp762A217; IBDBP1
Tractability: Antibody: UniProt predicts a signal peptide or a membrane-spanning region; the Human Protein Atlas places it where antibodies can reach.
Gene: Protein-coding gene on chromosome 12 (82,686,880 to 83,134,870, forward strand). Ensembl gene ENSG00000179104.
Subcellular location: Membrane; Endoplasmic reticulum
Subcellular location (Human Protein Atlas): Plasma membrane; Actin filaments
Gene Ontology:
Molecular function: dolichyl-phosphate-mannose-protein mannosyltransferase activity; protein binding; mannosyltransferase activity
Biological process: calcium ion homeostasis; protein O-linked glycosylation via mannose
Cellular component: endoplasmic reticulum; endoplasmic reticulum membrane; membrane
Genetic constraint (gnomAD): Loss-of-function variants: 32 observed, 67.27 expected, observed/expected ratio (o/e) 0.48, 90% interval 0.36 to 0.64. The upper end of that interval is the gene's LOEUF score, 0.64, which puts it in group 2 of 6, group 1 being the genes least tolerant of losing a copy. Missense variants: 835 observed, 953.99 expected, observed/expected ratio (o/e) 0.88, 90% interval 0.83 to 0.93. Synonymous variants: 376 observed, 373.59 expected, observed/expected ratio (o/e) 1.01, 90% interval 0.92 to 1.1.
Gene-disease validity (ClinGen):
ClinGen rates the evidence that TMTC2 causes each of these diseases.
nonsyndromic genetic hearing loss (autosomal dominant): Disputed. A disease characterized by hearing loss that is not part of a larger syndrome.
Homologues: Orthologues: chimpanzee TMTC2 (99% identical), macaque TMTC2 (97% identical), rabbit TMTC2 (97% identical), rat Tmtc2 (96% identical), mouse Tmtc2 (96% identical), dog TMTC2 (95% identical), pig TMTC2 (93% identical), guinea pig TMTC2 (92% identical), tropical clawed frog tmtc2 (83% identical), zebrafish tmtc2b (54% identical), Caenorhabditis elegans ttc-7 (10% identical). Paralogues in human: TMTC1 (30% identical), TMTC4 (30% identical), TMTC3 (30% identical), CFAP70 (13% identical), TTC7A (12% identical), IFT88 (12% identical), TTC7B (12% identical), TTC34 (11% identical), TTC6 (10% identical), BBS4 (10% identical), OGT (10% identical), TTC16 (9% identical), and 2 more.
Diseases named in the same sentence as TMTC2 in open-access papers:
TMTC2 is named in the same sentence as 14 diseases in open-access papers, as found by Europe PMC text mining. Sharing a sentence is not in itself a finding about the gene and the disease. The quoted sentences say what the papers report.
glaucoma (6 papers, 2012 to 2024). Increased pressure in the eyeball due to obstruction of the outflow of aqueous humor. "In humans, Diras3 and Tmtc2 are implicated in the onset of glaucoma, a progressive optic neuropathy caused by the loss of RGCs, further confirming the important role of Oc proteins and their target genes in the onset of human diseases." (PMID 39768162, 2024). "The first study was performed in a Japanese cohort, claiming that TMTC2 was a susceptible locus associated with primary open-angle glaucoma." (PMID 37255536, 2023). "ENS_06770 (Tmtc2) encodes an endoplasmic reticulum tetratricopeptide repeat-containing adapter protein involved in calcium homeostasis that has been associated with primary open-angle glaucoma." (PMID 33816460, 2021). "Later, a multiethnic GWAS study identified TMTC2 among many novel risk loci for glaucoma." (PMID 37255536, 2023). "Based on the gene profiling in the optic nerve head tissue, Cadm2, Cdkn2b, and Tmtc2 exhibit altered expression very early and across all stages of glaucoma (early to severe)." (PMID 29891935, 2018). "These included Angpt1, Ank, Cadm2, Fmnl2, Plce1, Thsd7a, and Tmtc2 at the novel POAG/glaucoma loci identified in the current study." (PMID 29891935, 2018).
auditory neuropathy spectrum disorder (4 papers, 2018 to 2025). "TMTC2 variants are associated with familial bipolar sensorineural hearing loss and auditory neuropathy spectrum disorders." (PMID 40564276, 2025). "Mutations in TMTC2 were previously reported in sensory organ disorders, such as sensorineural hearing loss and auditory neuropathy spectrum disorder." (PMID 37255536, 2023). "In epithelial patterning (CD−M5), Tmtc2, Hgf, and Ccdc50 were associated with NSHL and Ror1 with hearing loss and auditory neuropathy." (PMID 39684410, 2024).
sensorineural hearing loss (4 papers, 2018 to 2025). "TMTC2 is associated with non-syndromic sensorineural hearing loss (SNHL; via both GWAS and FS)." (PMID 33436046, 2021).
asthma (3 papers, 2015 to 2025). "A multi-stage GWAS study in children with childhood AD and asthma found new genetic loci (rs9357733 positioned in EFHC1 on chromosome 6p12.3 and rs993226 between TMTC2 and SLC6A15 on chromosome 12q21.3) that were specific for AD-asthma march phenotype." (PMID 35455494, 2022).
hearing loss (3 papers, 2018 to 2024). "TMTC2 is a gene that, outside this and one other study, had not been previously implicated in hearing loss." (PMID 29671961, 2018). "Furthermore, though other Tmtc family members, including TMTC2, have been implicated in hearing loss, there have previously not been any humans described with TMTC4-associated hearing loss." (PMID 37943620, 2023).
allergic disease (2 papers, 2015 to 2025). An immune response that occurs following re-exposure to an innocuous antigen, and that requires the presence of existing antibodies against that antigen. "We identified seven genome-wide significant loci, of which two susceptibility loci, in EFHC1 on chromosome 6p12.3 and between TMTC2 and SLC6A15 on chromosome 12q21.3 were associated with allergic disease for the first time." (PMID 26542096, 2015).
epilepsy (1 paper, 2024). A brain disorder characterized by episodes of abnormally increased neuronal discharge resulting in transient episodes of sensory or motor neurological dysfunction, or psychic dysfunction. "In contrast, P2RX7 and TMTC2 presented a trend opposite that of miR-211-5p, so we only focused on these upregulated genes in epilepsy." (PMID 38191407, 2024). "While it is possible that miR-211-5p may also affect epilepsy by targeting TMTC2, our current study primarily assessed P2RX7, which displayed the most significant upregulation as measured by qRT-PCR." (PMID 38191407, 2024). "Ultimately, 5 target genes were obtained, of which P2RX7 and TMTC2 were upregulated and CACNA1C, JPH3 and GRM1 were downregulated in epilepsy." (PMID 38191407, 2024).
cancer (1 paper, 2020). A tumor composed of atypical neoplastic, often pleomorphic cells that invade other tissues. "Multiple cancer survival-related genes were found in these genes, including CDH17, PTPRJ, SLC16A14, TMTC2, and NOTCH4." (PMID 32426342, 2020).
TMTC2 also shares sentences with these, for which no sentence is quoted: primary open-angle glaucoma (4 papers); eczema (2); atopic march (1); dementia (1); Optic neuropathy (1); tumor (1).